IL5RA (interleukin 5 receptor subunit alpha)
Diseases named in the same sentence as IL5RA in open-access papers (continued):
Sharing a sentence is not in itself a finding about the gene and the disease.
asthma (continued). "To date, the United States Food and Drug Administration (FDA) has approved six biologics for use in selected severe asthma patients: Omalizumab (anti-IgE); Mepolizumab, Benralizumab, Reslizumab (anti-IL5/anti-IL5Rα); Dupilumab (anti-IL4Rα); and Tezepelumab (anti-TSLP)." (PMID 38259298, 2023). "In patients with nasal polyposis (NP), the ratio of soluble to transmembrane IL-5Rα mRNA in polyp tissue was greater in NP patients with asthma than in patients without asthma." (PMID 34638583, 2021). "Anti-IL-5Rα therapy in patients with severe steroid-dependent asthma reduced blood and sputum eosinophils and IL-5Rα+ ILC2 but not total ILC2." (PMID 34630416, 2021). "A correct definition of asthma and CRS phenotype/endotype is crucial, taking into account the availability of novel biological therapies, such as anti-IgE, anti-IL-5/IL-5Rα and anti-IL4/IL-13Rα, which are dedicated to patients who do not respond to conventional asthma or CRSwNP therapies." (PMID 33805199, 2021). "Concerning the different types of asthma, IL5RA expression levels were elevated in both allergic and non-allergic asthma." (PMID 33644088, 2020). "In conclusion, we offer an anti–IL-5Rα humanized Ab, 5R65.7, which more potently inhibits IL-5–dependent eosinophil proliferation and induces NK cell–mediated ADCC against eosinophils from patients with severe asthma, as compared with a benralizumab analogue." (PMID 33488590, 2020). "Specifically, cg10159529 (IL5RA) and cg27469152 in the 3′UTR region of the EPX gene were highly significant in the asthma analysis and in our comparisons of ADEH+ patients versus healthy controls (FDR-adjusted q-value < 0.05) when not adjusting for eosinophils." (PMID 31443688, 2019). "Furthermore, low plasma levels of IL-5Rα were found in children with asthma exacerbations, whereas children with earlier age of asthma onset showed increased levels of IL-5Rα, providing firm evidence of implication of IL5RA on asthma." (PMID 30805318, 2019). "Although anti-IL-5 and anti-IL-5Rα agents did not reduce FeNO in all patients with severe asthma, recent evidence suggested that anti-IL-5 agents can reduce FeNO levels, and that responders to the agents were more likely to achieve clinical remission after 12 months." (PMID 41584312, 2025). "Indeed, previous reports in asthma or other eosinophilic diseases have shown no changes in IL-5Rα expression on circulating eosinophils after mepolizumab treatment, or even increased levels." (PMID 41394834, 2025). "Considering asthma, CRSwNP patients, with or without concomitant asthma, showed higher IL5RA expression than controls (10.3 ± 18.5 and 10.6 ± 8.26, respectively, p < 0.001), as well as both CRSwNP with AA and CRSwNP with NAA groups (10.2 ± 20.1 and 10.7 ± 18.1, respectively, p < 0.001)." (PMID 37509606, 2023). "Also notable is the lack of correlation between IL5RA expression and eosinophils in the CRSwNP group without asthma when the differences in expression between this group and controls were significant." (PMID 37509606, 2023). "In a study of the Danish asthma registry, decreasing Feno was found to be a predictor for remission in a cohort receiving anti-IL5/IL-5Rα therapy; however, decreasing Feno was not a predictor of remission in our cohort." (PMID 40810090, 2025). "Second, because anti-IL-5/IL-5Rα mAbs alone have not yet been approved for ABPA treatment, this study was limited to patients with comorbid asthma." (PMID 37015988, 2023). "Five monoclonal antibodies (mAb) targeting some molecules participating in type 2 (T2) inflammation (i.e., anti-IL4/13, anti-IL-5, anti-IL-5Rα, anti-IgE, anti-thymic stromal lymphopoietin (TSLP)) are now available for severe asthma and some of them are also indicated for CRSwNP." (PMID 37108417, 2023).
eosinophilia (17 papers, 2013 to 2025). "IL-5 acts on IL-5 receptor subunit α (IL5RA), causing eosinophilia." (PMID 34372824, 2021). "Eosinophilic/ANCA-negative: favor IL-5 or IL-5Rα inhibition, with escalation to IL-5Rα agents (e.g., benralizumab) in patients with persistent eosinophilia, relapse after IL-5 therapy, or preference for single-dose administration every 4 weeks." (PMID 41303621, 2025). "Following the allergen challenge, there is a notable rise in the percentage of CD34+ cells that express IL-5Rα in comparison to the levels observed in the bone marrow before allergen exposure, which is followed by blood and sputum eosinophilia." (PMID 39062104, 2024). "Vasculitic/ANCA-positive: prioritize B-cell-directed therapy (rituximab ± cyclophosphamide); IL-5 or IL-5Rα blockade may be added for eosinophilia and asthma control." (PMID 41303621, 2025). "In early-onset allergic asthma with eosinophilia could be used an anti-IL5/IL5Rα, dupilumab or tezepelumab, but the main reason to choose in first place omalizumab is more years of experience." (PMID 36452259, 2022). "It has been found that increased expression of IL5RA on CD34+ cells favors eosinophilopoesis and therefore may contribute to the subsequent development of blood and tissue eosinophilia, a hallmark of allergic inflammation." (PMID 23515576, 2013). "Heightened expression of IL-5Rα on CD34+ cells promotes eosinophil production, potentially contributing to the subsequent emergence of eosinophilia in both blood and tissues." (PMID 39062104, 2024). "When other eosinophilic asthma manifestations exist (nasal polyps, aspirin-exacerbated respiratory disease [AERD], atopic dermatitis or if eosinophilia persists after a short term of OCS), anti IL5/IL5Rα or dupilumab would be recommended." (PMID 36452259, 2022). "Given that for the targeting of IL-5Rα, only benralizumab has been clinically approved so far, alternative Abs are needed to give physicians the option of switching between anti–IL-5Rα Abs in the management of treatment-refractory SEA and other eosinophilia-related diseases." (PMID 33488590, 2020). "Thus, when comparing IL5RA expression with eosinophil count, we can observe some atypical cases with high gene expression despite not having eosinophilia." (PMID 37509606, 2023). "In an early onset allergic USA patient, independently of blood eosinophil count, omalizumab will be the first choice while in a late onset non-allergic USA patient with eosinophilia, an anti-IL5/IL5Rα, or dupilumab will be considered." (PMID 36452259, 2022).
allergic asthma (11 papers, 2012 to 2025). A asthma with a basis in a pathological type I hypersensitivity reaction. "In general terms, median levels of IL5RA expression in patients were almost twice as high as those in controls, being more pronounced in patients with CRSwNP only, with a peak in those with allergic asthma associated (almost threefold)." (PMID 37509606, 2023). "Eosinophils, which are central to the pathogenesis of allergic and non-allergic asthma, express high levels of surface IL-5Rα chain, as well as TSLPR, the IL-4Rα chain common to IL-4R and IL-13R, and the high-affinity receptor FcεRI." (PMID 34572466, 2021). "IL-5Rα expression has also been noted on neutrophils in the lungs of house dust mite sensitized mice and in the lungs of horses with heaves, an allergic asthma-like condition." (PMID 31415658, 2019). "One streaking feature was that IL5RA expression levels were significantly higher in non-allergic asthma patients with NP respect to non-allergic asthma patients without NP." (PMID 33644088, 2020). "Interestingly, the lower increase in IL5RA expression levels was observed in patients with non-allergic asthma (NAA) without NP (10.3 ± 11.2; P = 0.037)." (PMID 33644088, 2020). "In non-allergic asthma, omalizumab is not indicated, while an anti-IL5/IL5Rα, dupilumab, or tezepelumab could be considered." (PMID 36452259, 2022).
nasal polyp (9 papers, 2020 to 2026). "Novel biologic agents blocking the production or action of such cytokines, including, for instance, IL-5, IL-5Rα, IL-33 and immunoglobulin (Ig)E, have been developed and examined for treatment of chronic rhinosinusitis-related nasal polyps." (PMID 37375083, 2023). "In the literature, N-ERD patients have already shown a relationship between the development of nasal polyps and IL5RA levels." (PMID 37509606, 2023). "This could be due to reduced expression of IL-5Rα on eosinophils in nasal polyp tissue, a process attributed to IL-5Rα cleavage mediated by matrix metalloproteinases." (PMID 41178590, 2025). "Anti-IL-5 and anti-IL-5Rα in real-life studies have shown to significantly reduce eosinophils number in nasal polyps, the latter with a complete reduction in eosinophils- and neutrophils-infiltrated cells, with a significant reduction in the nasal polyp score (NPS) after 6 months." (PMID 37108417, 2023).
allergic disease (8 papers, 2015 to 2024). An immune response that occurs following re-exposure to an innocuous antigen, and that requires the presence of existing antibodies against that antigen. "Based on their experiences to date, most participants in this survey believe that anti-interleukin (IL)-5/IL-5Rα biologics are quite effective for most patients with SA, probably owing to the fact that in adult patients with uncontrolled SA, allergy is not the primary pathophysiologic mechanism." (PMID 34185809, 2021).
atopic dermatitis (8 papers, 2021 to 2025). "Benralizumab, an anti‐IL‐5Rα monoclonal antibody, significantly depleted blood and lesional skin MBP+ eosinophils in adults with moderate‐to‐severe atopic dermatitis." (PMID 40781582, 2025).
COVID-19 (6 papers, 2021 to 2025). A disease caused by infection with severe acute respiratory syndrome coronavirus 2. "Finally, a total of eleven differential factors related to COVID-19 disease severity were identified, including: TRAIL R1, IGFBP-1, IGFBP-4, VCAM-1, sFRP-3, FABP2, Transferrin, GDF15, IL-1F7 (also known as IL-37), IL-5Rα, and CD200." (PMID 34335566, 2021). "In addition, the levels of IL-5Rα, FABP2, CD200 and transferrin consistently showed the highest levels in the moderate group, indicating that these factors may serve as sensitive biomarkers reflecting COVID-19 disease severity." (PMID 34335566, 2021).
eosinophilic disorders (5 papers, 2021 to 2026). "Indeed, the expression of IL-5Rα mRNA isoforms is altered in a number of eosinophilic disorders." (PMID 34638583, 2021).
eosinophilic esophagitis (4 papers, 2018 to 2025). Eosinophilic esophagitis (EoE) is a chronic, allergic disease of the esophagus characterized clinically by symptoms of esophageal dysfunction (including vomiting, dysphagia, feeding disorders, food impaction and abdominal pain) which persist after treatment with proton pump inhibitors (PPIs). "Monoclonal antibodies against the IL-5 pathway, particularly mepolizumab, achieve dramatic eosinophil reduction in IL5RA-associated eosinophilic esophagitis by interrupting this critical cytokine-receptor axis." (PMID 41141324, 2025). "IL5RA variants in eosinophilic esophagitis (EoE) enhance IL-5 receptor signaling, driving tissue inflammation through exaggerated eosinophilic responses." (PMID 41141324, 2025). "Interleukin-5 (IL-5) has recently been shown to play a crucial role in eosinophil-mediated diseases, implying that an IL-5 receptor alpha chain (IL-5Rα) antibody (benralizumab) can be effective against eosinophilic esophagitis (EoE)." (PMID 38267847, 2024).
colitis (3 papers, 2019 to 2025). Inflammation of the colon. "The two studies referenced above demonstrated that IL-5RA antagonists ameliorate colitis through distinct mechanisms." (PMID 40475764, 2025). "Collectively, these studies underscore the critical role of eosinophil and IL-5RA signaling in IBD pathogenesis, with IL-5RA antagonist demonstrating significant potential in improving disease outcomes in DSS-induced colitis models." (PMID 40475764, 2025). "IL-13 (p = 0.05) and IL-5Rα (p < 0.05) were significantly increased in the TA-administered colitis group compared with the unadministered colitis group." (PMID 40333150, 2025). "In colitis mice, TA administration increased IL-13 and IL-5Rα levels compared to those in untreated colitis mice, suggesting that TA may exacerbate colitis symptoms." (PMID 40333150, 2025). "Additionally, it examined the expression of CCR3, CCL11, IL-5Rα, and TLRs in TA-treated normal and colitis mice to evaluate the role of TA in enhancing eosinophil-mediated inflammation through the modulation of these receptors and ligands." (PMID 40333150, 2025). "Moreover, mRNA expression of IL-5Rα was elevated in normal mice and colitis mice administered with TA." (PMID 40333150, 2025). "IL-5 promotes eosinophil production through IL-5Rα and contributes to the pathogenesis of IBD, while IL-5 receptor antagonists alleviate DSS colitis." (PMID 40333150, 2025). "Moreover, colitis mice treated with 50 μg TA exhibited significant increases in IL-13 and IL-5Rα levels, which likely contribute to the exacerbation of colitis symptoms rather than promoting resolution." (PMID 40333150, 2025). "The mRNA expression levels of Th2 cytokines as well as IL-17, IL-5Rα, and CCL11 were analyzed in TA-treated and TA-non-treated colitis mice." (PMID 40333150, 2025).
parasitic infections (3 papers, 2017 to 2023). "The results of this study suggested that IL-5 produced by the type-2 inflammatory response to parasite infection promoted induction of autoantigen-specific CD25+Il5ra+ T regulatory cells that reduced the severity of autoimmunity." (PMID 29163523, 2017). "IL-4 produced early in the response to parasitic infection may have contributed to the initial activation of antigen-activated Treg to induce expression of il5ra and subsequent dependence on IL-5." (PMID 29163523, 2017). "We also showed IL-5 treatment, as with parasitic infection, increased the number of CD4+CD25+ Treg that expressed Il5ra." (PMID 29163523, 2017). "Our interpretation of the effects of parasitic infection is that production of IL-4 and IL-5 by the activated Th2 cells and ILC2 accelerates the induction of autoantigen-specific Treg that express Il5ra, which in turn, reduced the severity of EAE." (PMID 29163523, 2017).
bronchiectasis (2 papers, 2021 to 2024). Segmental, irreversible dilation of the bronchial tree resulting in the accumulation of secretions which leads to obstruction. "Five bronchiectasis patients with a concomitant diagnosis of severe eosinophilic asthma were treated with anti-IL5 and anti-IL5-ra (i.e., two with benralizumab and three with mepolizumab)." (PMID 34356836, 2021).
Hodgkins lymphoma (2 papers, 2022 to 2023). A heterogeneous group of malignant lymphoid neoplasms of B-cell origin characterized histologically by the presence of Hodgkin and Reed-Sternberg (HRS) cells in the vast majority of cases. "Strikingly, Staege and his partners found that IL5RA was overexpressed in Hodgkin’s lymphoma cell lines which were resistant to CDDP." (PMID 35468881, 2022). "Interestingly, it was unveiled that IL5RA was upregulated in Hodgkin’s lymphoma cell lines resistant to cytotoxic drugs including CDDP." (PMID 35468881, 2022).
Multiple Myeloma (2 papers, 2023 to 2026). "Furthermore, IL5RA was associated with immune infiltration, immunogenic cell death-related genes, immune-checkpoint-related genes, and m6A in myeloma." (PMID 37236993, 2023). "After IL5RA-shRNA transfection in myeloma cells, cell proliferation, apoptosis, and drug sensitivity were detected." (PMID 37236993, 2023). "In vitro and in vivo experiments showed the involvement of IL5RA in apoptosis, proliferation, and drug resistance of myeloma cells." (PMID 37236993, 2023). "IL5RA was upregulated in myeloma and progressed smoldering myeloma." (PMID 37236993, 2023). "IL5RA shows the potential to be an immunogenic cell death-related predictor for myeloma." (PMID 37236993, 2023). "The significance of IL5RA in myeloma and immunogenic cell death remains unknown." (PMID 37236993, 2023).
Sepsis (2 papers, 2018 to 2019). Sepsis is defined as life-threatening organ dysfunction caused by a dysregulated host response to infection. "IL-5Rα expression on lung and blood neutrophils and macrophages was recently reported in humans in a sepsis model, where IL-5 was also shown to be protective in an eosinophil independent manner." (PMID 31415658, 2019). "IL-5RA is the receptor of IL-5, which has been proposed as a viable therapy for sepsis and is required for attraction and activation of eosinophils by Th2 cells." (PMID 30463588, 2018).
viral infections (2 papers, 2020 to 2023). "Since eosinophils serve as a host defender against parasitic, bacterial, and viral infections, eosinophil-depleting therapies, including anti–IL-5Rα Ab treatment, raise the potential risk of increased infections." (PMID 33488590, 2020).
ampullary carcinomas (1 paper, 2020). "Two ampullary carcinomas, two cholangiocarcinomas, a benign case of pancreatitis and a benign bile duct adenoma resulted in negative detection of IL-5Rα, supporting a specificity for cancerous pancreatic ductal cells." (PMID 32552827, 2020).
anaphylaxis (1 paper, 2023). An acute hypersensitivity reaction that occurs from exposure to an allergen. "There were no severe adverse events, including episodes of anaphylaxis, during treatment with anti-IL-5/IL-5Rα mAbs." (PMID 37015988, 2023).
autoimmune disease (1 paper, 2017). A disorder resulting from loss of function or tissue destruction of an organ or multiple organs, arising from humoral or cellular immune responses of the individual to their own tissue constituents. "Additional Ets1 target genes include ones important for immune function such as Il5ra, Tlr1, Traf4, and Ltk, but that not yet been implicated as susceptibility loci for autoimmune disease." (PMID 28439269, 2017).
bipolar disorder (1 paper, 2023). A disorder of the brain that causes unusual shifts in mood, energy, activity levels and the ability to carry out day-to-day tasks. "A previous study found that IL5RA and PIK3R6 were upregulated in lithium-treated bipolar disorder patients." (PMID 37186582, 2023).
bladder cancer (1 paper, 2012). "In the present study, both IL-5 and IL-5Rα were detected by RT-PCR and immunoblot in bladder cancer cells." (PMID 22962576, 2012).
breast tumor (1 paper, 2022). "Common β chain (CD131), IL-3Rα (CD123), and IL-5Rα (CD125) were detectable on the surface of the breast tumor cells in mice." (PMID 35657353, 2022).
cardiac failure (1 paper, 2021). "For example, IL5RA is involved in cardiac failure, familial combined hyperlipidemia, and juvenile arthritis, and also Down Syndrome." (PMID 33546175, 2021).
conjunctivitis (1 paper, 2026). Inflammation of the conjunctiva of the eye. "Some allelic variants of genes were found to be associated with conjunctivitis (FLG), rhinitis (KIF3A), bronchial asthma (IL5RA) comorbidities and high IgE levels (ADAM33)." (PMID 42039188, 2026).
eczema (1 paper, 2024). "A substantial correlation was identified between eczema phenotypes and s-IL-5Rα." (PMID 39062845, 2024).
inflammatory bowel disease (1 paper, 2025). A spectrum of small and large bowel inflammatory diseases of unknown etiology. "This study aimed to analyze tissue eosinophils and interleukin-5 receptor-α subunit (IL-5RA) expression on eosinophils in inflammatory bowel disease (IBD)." (PMID 40475764, 2025).
intervertebral disc degeneration (1 paper, 2022). "A study verified that miR-495-3p can play a role in intervertebral disc degeneration (IVDD) by inhibiting inflammation and apoptosis of human nucleus pulposus cells by targeting IL5RA." (PMID 35354479, 2022).
ischemic stroke (1 paper, 2016). A stroke disorder caused by obstruction of blood flow to the brain, due to thrombotic (local blood clot formation) or embolic (due to a blood clot or other material traveling from another site) event. "Genetic studies have identified single nucleotide polymorphisms (SNPs) that are associated with increased risk of CAD in the interleukin-5 gene (IL5) and increased risk of ischemic stroke in the interleukin-5 receptor alpha subunit gene (IL5RA)." (PMID 26821299, 2016).